IFNLR1 (interferon lambda receptor 1)
Diseases named in the same sentence as IFNLR1 in open-access papers (continued):
Sharing a sentence is not in itself a finding about the gene and the disease.
infection (continued). "GSIB4+ basal epithelial cell upregulation during infection appeared to be both type I and III IFN-dependent, as this phenotype was lost in Ifnar1−/− and Ifnlr1−/− mice." (PMID 38530032, 2024). "Using single-cell RNA-sequencing (scRNA-seq), we measured the expression of either type I (Ifnar1 and Ifnar2) or type III (Ifnlr1 and Il10rb) IFN receptor subunits in mouse lung cells on day 1 post-infection." (PMID 38530032, 2024). "Because IFNλ has been shown to impede super-infection clearance in a number of different studies, we hypothesize that the presence of IFNLR1 on other cell types, including the epithelium, in the incomplete knockout models presented dampens the phenotypes seen when compared to global IFNLR1-/- mice." (PMID 39178311, 2024). "Ifnlr1−/− mice exhibited higher lung HMPV titers than WT or Ifnar1−/− mice by day 5 and day 7 post-infection and delayed viral clearance, showing that IFN-λ contributes to limiting HMPV replication." (PMID 38530032, 2024). "We observed that infection of WT BMDC led to an upregulation of CD86 compared with mock BDMC, and this upregulation upon infection was significantly reduced in Ifnlr1–/–." (PMID 38973611, 2024). "Using A549 wild-type (WT), IFNAR1 knockout (KO), IFNLR1 KO, and IFNAR1-IFNLR1 double-KO cell lines, we found that both IFN-β and IFN-λ are necessary for maximum protection against subsequent infection." (PMID 36326278, 2022). "Using Ifnlr1 IEC-cKO mice, we found increase in IEC infection by mRV at early stages of infection compared to Ifnlr1flox/flox littermates." (PMID 35137688, 2022). "We observed that infection with RSV or IAV leads to the robust activation (phosphorylation) of STAT1 and STAT2 in A549 WT cells as well as IFNLR1 KO cells." (PMID 36326278, 2022). "This somehow exhaustive effect of USUV on glycolysis of A549 cells with IFNAR/IFNLR1 KO was also present through a significant drop in the ECAR metabolic potential, which was also noted after infection of Vero cells." (PMID 35186796, 2022). "We determined that the observed differences in antibody titers on day 7 post-infection were reflected in the number of MSP-specific plasmablasts, as Ifnlr1−/- mice had increased numbers and percentages of MSP-specific plasmablasts." (PMID 32407154, 2020). "We infected WT or Ifnlr1-/- mice with CR6 or CR6Δcasp and monitored shedding in the stool over time, and persistence in the colon at 21 days post-infection." (PMID 31329638, 2019). "Upon infection with Udorn virus, expression of the IFN-λ genes in Ifnar1−/− mice returned to comparable levels of WT and Ifnlr1−/− mice within two days." (PMID 29651984, 2018). "To exclude unwanted interference from virus-induced endogenous IFN, we used Ifnlr1−/− and Ifnar1−/− mice and treated them intranasally with IFN-α or IFN-λ, respectively, one day before infection with the Udorn virus." (PMID 29651984, 2018). "IFNLR1 is part of the receptor system for type III interferons, which play a significant role in innate immunity at epithelial surfaces, including potentially in the mammary gland’s defense against infection." (PMID 41514760, 2025). "The differences in ISG expression were not dependent on changes in IFN gene expression, as Ifnl3, Ifnb1, and Ifna12 were not vastly altered throughout the course of infection (days 1, 2, 3, or 5 p.i.)between WT and Ifnlr1–/– mice." (PMID 38973611, 2024). "In contrast only in IFNAR/IFNLR1 double KO cells a significant increase in basal glycolysis of USUV strain Europe 3 and a strain-independent significant reduction in stressed ECAR occurred after USUV infection." (PMID 35186796, 2022). "However, the protection offered by IEC expression of Ifnlr1 was lost by the middle and late stages of infection, consistent with the ability of mRV to antagonize induction of IFN responses once infection is established." (PMID 35137688, 2022).
infection (continued). "Our mixed bone marrow chimera experiments demonstrate that the shift toward an effector response in Ifnlr1−/- mice during blood-stage infection is not mediated by direct IFNλ signals on CD4 + T cells, in keeping with observations using similar approaches." (PMID 32407154, 2020). "To test this hypothesis, we infected WT or Ifnlr1-/- mice with our panel of MNV strains and quantified IEC infection at three days post-infection by flow cytometry." (PMID 31329638, 2019). "However, IEC infection was increased in Ifnlr1-/- mice relative to WT mice, indicating that IFN-λ limits early establishment of infection in the IEC reservoir." (PMID 31329638, 2019). "CR6 and CR6-VP1CW3 were detected in an average of 40 IECs per million in Ifnlr1-/- mice, but we did not detect significant infection of IECs by NS1/2 cleavage mutants." (PMID 31329638, 2019). "However, we observed similar inflammatory cell recruitments, as demonstrated by this study between wild type and IFNLR1 KO mice post infection with Pseudomonas, along with no upregulation of interferon levels beyond 4 h, as reported in this study." (PMID 39455422, 2024). "(A) Standard intranasal delivery of virus inoculum: WT (n = 6), Ifnar1−/− (n = 4) and Ifnlr1−/− (n = 7) mice were intranasally infected with 104 PFU of SC35M in a volume of 40 μl, and viral titers in the lungs were determined on day three post infection by plaque assay." (PMID 29651984, 2018). "By contrast, no symptoms were observed after infection of adult Ifnlr1-/- and wild-type mice." (PMID 25849543, 2015). "Interestingly, wild-type and Ifnar1−/− mice, but not Ifnlr1−/− mice, showed a decrease in lung ciliated epithelial cells early post-infection, suggesting IFN-λ may also drive this phenotype." (PMID 38530032, 2024). "To explore whether SECoVs infection affects IFN receptors expression, we next compared the receptor expression of the three types of IFNs, including type I IFN receptors (IFNAR1 and IFNAR2), type II IFN receptors (IFNGR1 and IFNGR2), and type III IFN receptors (IL10RB and IFNLR1)." (PMID 35126380, 2021). "Infection of BEAS-2B cells with various MOI of PR8 and FBXO45 silencing also led to a substantial increase in ISG expression, an effect not observed after IFNLR1 cellular depletion." (PMID 36379255, 2022). "At the early time post-infection, lamina propria cells that readily respond to exogenous type I IFN did not contain detectable levels of Mx1 in wild-type or Ifnlr1-/-, suggesting that type I IFN production was low." (PMID 25849543, 2015). "By contrast, Ifnlr1-/- mice failed to mount a proper IFN response on day 1 and showed a strongly attenuated response on day 4 post-infection." (PMID 25849543, 2015). "We added a blocking anti-Ifnar1 monoclonal antibody (mAb) to OVX, hormone treated, WT, and Ifnlr1−/− mice as ZIKV fails to antagonize type I IFN signaling in murine cells; indeed, in the absence of anti-Ifnar1 mAb treatment, little infection was observed at 7 dpi in WT or Ifnlr1−/− mice." (PMID 30655513, 2019). "Infection of mice by persistent MNoV strain CR6 was found to be enhanced by the presence of intestinal commensal bacteria, a dependence that was abrogated in mice lacking Ifnlr1, but not Ifnar1." (PMID 29361691, 2018). "Moreover, depletion of IFNLR1, but not IFNAR1, resulted in a 3-fold increase in the HEV RNA abundance and infectious virus production, suggesting that HEV replication is restricted by the type III IFNs induced by infection." (PMID 28558073, 2017). "Interestingly, in mice lacking Ifnlr1, Stat1, or Irf3, all important molecules for IFN-λ induction or signaling, MNoV establishes infection even in the absence of commensal microbes, implicating IFN-λ in regulation of these transkingdom viral–bacterial interactions." (PMID 28713375, 2017).
tumor (14 papers, 2011 to 2026). "Next, using a publicly available single cell RNA sequencing dataset from lung cancer tumors, we found IFNLR1 expression to be significantly decreased in malignant epithelial cells compared to normal epithelial cells from the same tumor." (PMID 40012911, 2024). "Attempts with generating different murine cancer cell lines stable expressing IFNλ and subsequent engraftment in IFNLR1 wildtype mice shows tumor clearance." (PMID 40012911, 2024). "Overall, 87% of WT mice and 100% of single IFNR-deficient mice survived to the experimental endpoint and had similar tumor burdens in the large intestine with a mean tumor burden of 4.6, 4.3, and 2.3 in WT, Ifnar1−/− mice, and Ifnlr1−/− mice, respectively." (PMID 33976143, 2021). "Importantly, type III interferons such as IFN-λ have been shown to inhibit tumor cell proliferative activity and activate neoplastic cell apoptosis, perhaps via IFNLR1 ligation." (PMID 36379255, 2022). "Hence, it is conceivable that within the tumor microenvironment, the concentrations of IFNLR1 are exquisitely controlled by FBXO45 such that the robustness of signaling events downstream of IFN-λ–receptor activation (JAK-STAT1) impacts tumorigenesis." (PMID 36379255, 2022). "The selective downregulation of IFNLR1 expression in cancer cells could be seen as an immune escape mechanism evolved during cancer development which allows cancer cells to secrete IFNλ to support immunomodulation of the tumor microenvironment while avoiding being affected themselves." (PMID 40012911, 2024). "Due to the lower expression of IFNLR1 in most cell types, IFN-III offers a more selective targeted anti-tumor ability with fewer side effects compared to IFN-I." (PMID 37809098, 2023). "However, neither IFNLR1 nor hGPC1 correlated with tumour recurrence until 12 months after surgery, unlike IL-10R2." (PMID 38643339, 2024).
cancer (8 papers, 2011 to 2025). A tumor composed of atypical neoplastic, often pleomorphic cells that invade other tissues. "Rescuing IFNLR1 expression by CRISPRa in multiple cancer cell lines sensitization them to IFNλ-stimulation and resulted in significant reduction in cell viability." (PMID 40012911, 2024). "We find that IFNλ serves as a better marker of STING pathway activation in epithelial cancer cells than IFNβ, and that cancer cell-specific downregulation of IFNLR1 prevents autocrine and paracrine IFNλ signaling." (PMID 40012911, 2024). "Here, we report the regulation of STING-mediated IFNλ signaling in NSCLC, with a focus on IFNLR1 expression and the potential of chemotherapy induced IFNλ signaling as a therapeutic target in cancer treatment." (PMID 40012911, 2024). "When treating with recombinant IFNλ, both cancer cell lines were unaffected by the treatment but upon CRISPRa of IFNLR1 we observed a significant drop in cell viability of 20-40%." (PMID 40012911, 2024). "Expression of IFNLR1 was found downregulated in the cancer cell lines compared to the benign epithelial cell line Nuli-1." (PMID 40012911, 2024). "Re-expression of IFNLR1 on cancer cell lines was achieved using CRISPR activation (CRISPRa) followed by evaluating chemotherapy-induced apoptosis using flow cytometry assays." (PMID 40012911, 2024). "Downregulation of IFNLR1 can be an immune evasion mechanism developed by cancer cells to avoid responding to endogenous type III IFNs." (PMID 40012911, 2024). "In our work, we found that this could be targeted by upregulating IFNLR1 and thereby sensitizing the cancer cells to IFNλ leading to reduced viability." (PMID 40012911, 2024). "With improvement of mRNA therapeutics and lipid nanoparticle delivery, we may in the future explore if selective upregulation of IFNLR1 in cancer cells support better overall survival when combined with traditional cancer therapies." (PMID 40012911, 2024). "We therefore explored whether IFNLR1 up-regulation by HDAC inhibitors renders cancer cells sensitive to the antitumor properties of IFN-λ." (PMID 24409098, 2014). "Finally, understanding how and why cancer cells silence the expression of IFNLR1 may give us novel cancer drug targets for the future." (PMID 40012911, 2024). "The tissue-dependent expression of IFNLR1, particularly in epithelial cells, raises an interesting question – will the selective specificity make IFNλ a better alternative for treating cancer patients with NSCLC and other cancer with epithelial origin?" (PMID 40012911, 2024).
bacterial infection (1 paper, 2024). "Global IFNLR1-/- mice have reduced bacterial burden 24 hours post bacterial infection compared to WT mice, consistent with previous reports where modulation of IFNλ alters bacterial burden." (PMID 39178311, 2024). "Global IFNLR1-/- mice in our study had decreased IL-10 6 hours post bacterial infection compared to WT mice, indicating that IL-10 production or lack thereof in IFNLR1-/- mice may also contribute to increased IL-17 levels in the lung." (PMID 39178311, 2024). "Overall, phagocytic cells from IFNLR1-/- mice, including macrophages and monocytes, neutrophils, and dendritic cells, had a significantly higher frequency and total number of dsRed+ cells at both 6 and 24 hours post bacterial infection without any alteration in recruited numbers into the lung." (PMID 39178311, 2024).
intestinal disease (1 paper, 2023). "To investigate the role of type I and type III IFNs in controlling MNV intestinal disease, we also infected Ifnar1−/− and Ifnlr1−/− mice with each virus." (PMID 37142696, 2023). "Yet no study examining MNV infection in Ifnar1−/− or Ifnlr1−/− mice measured intestinal disease, using instead nonspecific virulence measures of weight loss and lethality or virus titers to assess the role of specific classes of IFNs." (PMID 37142696, 2023).
IFNLR1 also shares sentences with these, for which no sentence is quoted: mammary tumor (2 papers); allergic rhinitis (1); ankylosing spondylitis (1); asthma (1); coronary heart disease (1); diabetes (1); E. coli infection (1); endotoxemia (1); esophageal carcinoma (1); fibrosarcoma (1); hidradenitis suppurativa (1); infectious disease (1); leukoaraiosis (1); leukopenia (1); melanoma (1); mesothelioma (1); multiple sclerosis (1); osteosarcoma (1); pancreatic cancer (1); prostate carcinoma (1); psoriatic arthritis (1); SARS-CoV infection (1); Sepsis (1); type 2 diabetes (1); ulcerative colitis (1); vitiligo (1); whipworm infection (1).